LINC00994 (long independently transcribed non-coding RNA 994)
Gene: Long non-coding RNA gene on chromosome 3 (64,078,361 to 64,087,363, reverse strand). Ensembl gene ENSG00000189196.
Diseases named in the same sentence as LINC00994 in open-access papers:
LINC00994 is named in the same sentence as 2 diseases in open-access papers, as found by Europe PMC text mining. Sharing a sentence is not in itself a finding about the gene and the disease.
LINC00994 shares sentences with these, for which no sentence is quoted: gastric cancer (1 paper); pancreatic cancer (1).